INS (insulin)
Diseases named in the same sentence as INS in open-access papers (continued):
Sharing a sentence is not in itself a finding about the gene and the disease.
diabetes (continued). "For additional details, a table with insulin dose recommendations depending on ketone levels was published in the ISPAD Clinical Practice Consensus Guidelines 2018: Sick day management in children and adolescents with diabetes for suggested actions." (PMID 38785359, 2024). "Insulin levels were higher in people with type 1 diabetes, as compared to the control group without diabetes (214 ± 22 mE/L vs 102 ± 11 mE/L, p = 0.003)." (PMID 38376580, 2024). "We did not observe a relationship between the insulin administration schedule and nutritional status (BMI z-score), duration of diabetes, insulin administration method, and PAL." (PMID 38534969, 2024). "Patients in the groups of inadequately controlled diabetes and unrecognized diabetes took longer to arrive at target glucose, and more doses of insulin were used than in the groups of controlled diabetes and no diabetes." (PMID 38330019, 2024). "Diabetes Mellitus, which is a chronic metabolic disease, occurs when the pancreas does not produce enough insulin or when the body cannot effectively use the insulin it produces." (PMID 39548327, 2024). "The authors emphasize that the DIACAMP study was not a typical educational summer camp, because diabetes-specific training was kept to a minimum, and time-intensive documentation of carbohydrates, insulin doses and physical activity was not required." (PMID 39329826, 2024). "The patient’s phenotype is not in keeping with type 1 diabetes mellitus as she is insulin resistant with a high c-peptide and insulin when measured 21 years following diabetes diagnosis and is not ketone prone." (PMID 38461278, 2024). "Lack of insulin leads to hyperglycemia (high levels of blood glucose), the clinical indicator for diabetes." (PMID 39684575, 2024). "Diabetes mellitus is classified into three major types: type 1 (insulin-dependent), type 2 (noninsulin-dependent), and gestational diabetes mellitus." (PMID 38883868, 2024). "In patients with diabetes mellitus, insulin is either not produced or unable to attach to the cell to allow glucose to enter." (PMID 38686006, 2024). "In contrast, the findings of a substantial randomized controlled trial demonstrated unequivocal reductions in mortality associated with intensive insulin therapy for ICU patients, regardless of prior diabetes diagnosis." (PMID 38836227, 2024). "Diabetes mellitus (DM) is a chronic noncommunicable disease (NCD) characterized by persistent high blood glucose levels in which the body cannot make enough insulin or use it efficiently." (PMID 38646396, 2024). "Fourth, although many individuals with T2D did not have diabetes autoantibodies measured, only a very small subset (4.2%) persistently required insulin therapy, where we cannot entirely exclude the possibility of T1D." (PMID 38231515, 2024). "Any diabetes medicine taken by the patients can be categorized into the following nine categories: Metformin, Sulfonylurea, Pioglitazone, DPP-4- Inhibitor, GLP-1-RA, SGLT2-Inhibitor, Basal Insulin, Prandial Insulin, and Mixed Insulin." (PMID 38617952, 2024). "In healthy individuals without diabetes, the initial response to low blood sugar levels is a reduction in insulin secretion, even before the plasma glucose concentration reaches hypoglycemic levels." (PMID 38397994, 2024). "Type 1 diabetes mellitus (T1DM), also referred to as juvenile-onset diabetes or insulin-dependent diabetes mellitus, is a chronic autoimmune disorder marked by targeted destruction of insulin-producing beta cells in the pancreatic islets of Langerhans." (PMID 39769454, 2024). "This proposal is supported by evidence that women with increasing severity of insulin resistance during pregnancy (defined by insulin treatment during GDM pregnancy) have higher morbidity risk later in life; even in the absence of subsequent diabetes." (PMID 39497166, 2024).
diabetes (continued). "Our previous study investigated glucometabolic indices in patients with PD, revealing significant correlations between impaired fasting glucose, insulin resistance, the PD glucose load, and aortic stiffness, particularly in patients without diabetes on PD." (PMID 39598185, 2024). "The amount of DME and RT in peripheral sectors were both independent of systemic factors such as BMI, duration of diabetes, duration of insulin intake, retinopathy severity, and HbA1c levels." (PMID 39064281, 2024). "Diabetes mellitus is a metabolic disease characterized by a congenital (type I insulin-dependent) or an acquired (type II non-insulin-dependent) inability to transport glucose from the blood to the cells." (PMID 38474441, 2024). "It is hypothesized that in type 2 diabetes mellitus pathogenesis, oxidative stress induces the expression of UCP2, resulting in reduced ATP synthesis in beta cells that results in slower insulin response to glucose levels." (PMID 39561140, 2024). "We addressed body composition, glucose control and insulin action at both whole-body and tissue level in individuals with obesity and no diabetes." (PMID 38656372, 2024). "A new class of diabetes drugs has been developed: SGLT-2 inhibitors, which allow the kidneys to excrete more glucose; GLP-1 agonists, which increase insulin secretion; and iminosugars, such as 1-deoxynojirimycin, found in mulberry, which can inhibit gut glucosidase." (PMID 39063270, 2024). "Numerous prospective studies utilizing the HOMA-IR index to assess IR demonstrate that IR substantially increases individual diabetes or CVD risk in patients with CMS, suggesting that CMS does not equate to an insulin-resistant phenotype." (PMID 38402393, 2024). "In healthy people, insulin would regulate TRPM6 channel activity, but this may be impaired in diabetes." (PMID 38279093, 2024). "Diabetes is a common complication in individuals with ACP, often necessitating insulin therapy." (PMID 40729217, 2024). "In humans without diabetes, chronic hyperglycemia via glucose infusion has been shown to increase intramyocellular glycogen content, reduce insulin-stimulated GS activity, and reduce insulin sensitivity." (PMID 38435452, 2024). "Second, our data was limited in determining participants’ treatment regimen for diabetes (ie, anti-diabetic oral medications vs injectable insulin) and did not include participants’ specific medications." (PMID 39058533, 2024). "In diabetes the body is not able to utilize insulin or, in some cases, is not able to produce insulin." (PMID 39598340, 2024). "Diabetes mellitus (DM) is a chronic metabolic disease due to absence of insulin secretion or to insulin resistance and impaired pancreatic islet secretion combined in many different phenotypes." (PMID 39333854, 2024). "This might be because educated personnel, e.g., in-hospital diabetes teams with CGM competencies, and operational insulin titration algorithms might be imperative in achieving optimal use of telemetric CGM." (PMID 38711112, 2024). "This situation may influence access to insulin and SMBG devices in Indonesia with the increasing prevalence of diabetes." (PMID 39361609, 2024). "We observed a significant negative correlation between T2DM duration and PMI, with insulin-using patients having a much longer diabetes duration than those using oral antidiabetic medications." (PMID 39058051, 2024). "In the unmatched sample, statistically significant differences in exposure to TCM decoctions were observed based on age, sex, BMI, duration of diabetes, HbA1c, FPG, fasting insulin levels, C-peptide levels, TCM syndrome diagnosis, and the presence of several comorbidities." (PMID 39101135, 2024). "This study did not investigate diabetes development in the model, showing only that older mice under glucose challenge were slower to clear the glucose, but baseline glucose and insulin levels were not altered." (PMID 38397785, 2024).
diabetes (continued). "Type 2 diabetes mellitus (T2DM) is a metabolic disorder resulting from a lack of insulin cellular response (insulin resistance) leading to subsequent hyperglycaemia." (PMID 38474098, 2024). "For example, a study in rats with ME1 deficiency found that ME1 may promote adiposity and hepatic steatosis and induce circulating insulin and leptin, supporting the therapeutic targeting of ME1 for obesity, diabetes, and hepatic steatosis." (PMID 38836220, 2024). "Many patients with T2DM on insulin are not optimally controlled despite receiving standard diabetes education counselling." (PMID 39020348, 2024). "Therefore, we hypothesized that the activation of CXCR1/2 may have a detrimental role in the insulin sensitivity, thus inducing resistance and its inhibition may have positive effects on improving insulin sensitivity and preventing or treating metabolic disorders such as diabetes mellitus." (PMID 39627194, 2024). "American Indians also presented at an earlier age for TAVR and were significantly more likely to use tobacco and have diabetes mellitus treated with insulin than non-American Indians." (PMID 37129786, 2024). "We found that diabetes treatments, such as measurement and insulin injections, were discontinued when the patients were no longer eating and drinking, regardless of the patient’s diabetes type." (PMID 39390487, 2024). "Type 2 diabetes mellitus (T2DM) is a metabolic disorder that occurs as a result of insulin resistance and impaired insulin production by islet β cells in the pancreas; this condition leads to elevated blood glucose levels, resulting in increased glycated hemoglobin (HbA1c) levels." (PMID 39292676, 2024). "It underscores the role of physical activity in enhancing insulin sensitivity and glycemic control, offering a non-pharmacological strategy to mitigate diabetes-related complications in CKD patients." (PMID 38689329, 2024). "Patient information: a 38-year-old female patient, nulligest with Down syndrome, no family history of breast cancer, type 1 diabetic on insulin for 12 years with no control of her diabetes." (PMID 39220553, 2024). "Despite no previous or family history of diabetes, she developed diabetic ketoacidosis following treatment, requiring continuous insulin infusion." (PMID 39044884, 2024). "The only patient on insulin who did not require admission for a diabetes-related complication also did not require enteral feeding." (PMID 38392055, 2024). "Of the 168 individuals with HNF1B-diabetes, for whom treatment data after the genetic diagnosis was available, 132 (79%) used insulin, but it is not known if other medications had been tested." (PMID 39025920, 2024). "Notably, plasma levels of sIR have been found to be increased in patients with diabetes and to correlate with glucose concentrations, consistent with a role for MT1-MMP activity in modulating insulin sensitivity." (PMID 38246235, 2024). "T1DM, Type 1 diabetes mellitus; T2DM, Type 2 diabetes mellitus; GDM, Gestational diabetes mellitus; FI, Fasting insulin; FG, Fasting glucose; HbA1c, Hemoglobin A1c; MR-PRESSO, Mendelian randomization pleiotropy residual sum and outlier; Q value, the statistics of Cochran’s Q test." (PMID 38539234, 2024). "Classical clinical diagnostic features for recognizing MODY are young age at diabetes onset (< 25 years), family history of diabetes in a parent, evidence of residual insulin secretion, and the absence of islet cell autoimmunity." (PMID 39420387, 2024). "However, strikingly, the INS-construct and IGRP-construct expressing BDC2.5 eTregs protected against diabetes, in spite of the fact that the antigen-specific construct is only transiently expressed." (PMID 39351219, 2024). "In Sestrin-lacking mice, insulin responsiveness was defective, which promoted high-fat diet-induced insulin resistance and diabetes progression." (PMID 39309448, 2024).
diabetes (continued). "Diabetes is a metabolic disease that occurs when the body is unable to make enough insulin, or when insulin produced by the body is not functioning the way it should to control the blood glucose level to baseline level, consequently causing hyperglycemia." (PMID 38846325, 2024). "This risk was higher in both people with diabetes using insulin (aHR 1.51, 95% CI 1.31-1.74, P<0.001) and not using insulin (aHR 1.22, 95% CI 1.13-1.33, P<0.001), compared with those without diabetes." (PMID 38760264, 2024). "Herein, we introduce a novel modification of the STZ‐induced diabetes model in the C57BL/6J strain to increase the survival rate without needing insulin application while reducing the overall effort in the model induction." (PMID 39350510, 2024). "The association between high WC and favorable functional outcome was not affected by fasting insulin levels or homeostatic model assessment for insulin resistance and was only found in patients without diabetes (P = 0.02 for heterogeneity)." (PMID 38206990, 2024). "The mean age was 69.89 years, 95.14% were male, and 32.32% were not using oral medication or insulin to treat their diabetes." (PMID 38540606, 2024). "In this study, the 24 rats that developed diabetes did not receive insulin treatment and survived for 20 days without mortality." (PMID 39070316, 2024). "Information on the degree of glycemic control and insulin dose requirements are not available for comparison although the degree of dysglycaemia was potentially less than our case as diabetes was identified in pregnancy only." (PMID 38461278, 2024). "In persons suffering from diabetes, either insulin is not produced by the body which is Type 1 diabetes, or the produced insulin is not used effectively by the body which is Type 2 diabetes." (PMID 38371502, 2024). "Conversely, healthy men and women with diabetes demonstrated weak and negative correlations (rho coefficients of −0.2777 and −0.2639, respectively) between insulin and HGF." (PMID 38654922, 2024). "Other reports from Ballinger’s group used pronuclear transfer to introduce mtDNAs from different mouse strains, showing altered insulin sensitivity and glucose metabolism consequent to the mtDNA differences, but diabetes complications were not studied." (PMID 38397785, 2024). "There are numerous advantages of using an SGLT-2 inhibitor compared to other diabetes medications, most of which stem from its mechanism of being independent of insulin levels and sensitivity." (PMID 38910717, 2024). "The most notable exception was evident in the incidence of fatigue; here participants who used insulin reported having levels of fatigue higher than or equal to those without diabetes." (PMID 38412008, 2024). "Although the etiology of diabetes mellitus is quite complicated, some studies indicated that it can be attributed to lack of insulin secretion or insulin resistance or both." (PMID 39040674, 2024). "Intriguingly, in our study, we observed that TIR treatment prevented the HG induced mRNA and protein downregulation of GLUT3 along with GLUT1, GLUT4, and SORBS1, a protein that takes part in diabetes pathogenesis, and regulates GLUT4 translocation affecting neuronal insulin resistance." (PMID 38287296, 2024). "Our assessments of insulin adjustment skills, though created and reviewed by specialists in diabetes care and education, were not validated quizzes as no such measures exist in the low-resource setting, to our knowledge." (PMID 38190377, 2024). "Neither access to a diabetes nurse nor other support staff factors with relevance for diabetes follow-up related to the chance of reaching HbA1c <7.0% (53 mmol/mol) with insulin." (PMID 38116986, 2024). "This trend remained in all subsequent models, independent of the duration of diabetes, glucose metabolism, the use of statins or fibrates, or insulin." (PMID 38791405, 2024).
diabetes (continued). "Although the participants did not have diabetes, these findings suggest the potential benefits of managing postprandial glucose and insulin levels." (PMID 38540910, 2024). "Similarly, in mice, oral verapamil lowered TXNIP expression, increased endogenous insulin levels, and reduced β-cell apoptosis, rescuing the mice from streptozotocin (STZ)-induced diabetes." (PMID 38891081, 2024). "When exercising while on insulin and having diabetes, the patient should not inject oneself on the thighs." (PMID 38299525, 2024). "Regarding the pharmacists, half of them believed that diabetes is better controlled once insulin is started, so they can convince the patients who refuse to take insulin and those who believe that insulin has no privilege over oral hypoglycemic drugs." (PMID 38594659, 2024). "Nevertheless, studies have demonstrated that patients with MS, with or without diabetes, present with insulin resistance and a significant reduction in insulin secretion." (PMID 38818523, 2024). "This system categorizes individuals with diabetes into four distinct groups: 1) A+β-: Autoantibodies present, β-cell function absent; they need to be treated with exogenous insulin for life." (PMID 39634998, 2024). "Furthermore, the depression of plasma glucose and lipid levels in diabetic animals by both sarpogrelate and insulin treatments may represent a shift in substrate utilization by MT to maintain the energy status of the heart as well as to reduce the development of oxidative stress in diabetes." (PMID 39057635, 2024). "HOMA-IR, insulin, glucose level, and HbA1c were not included because these measurements are routinely used in clinical practice for diabetes diagnosis." (PMID 39589852, 2024). "In contrast, the majority of women with GDM and nearly all women with pre-existing diabetes were treated with insulin, with or without metformin." (PMID 40071056, 2024). "Insulin and noninsulin diabetes medication purchases for patients based on data 1 year before index and EOS (year 2019)." (PMID 38273701, 2024). "This indicates that the metabolome is highly sensitive to the presence or absence of insulin in T1D, potentially driving diabetes complications." (PMID 39195532, 2024). "P/T ratio is commonly used only in the context of therapeuticinsulins since endogenously secreted insulin in individuals without diabetes closely andconstantly matches glucose excursions." (PMID 38224978, 2024). "We found that fenugreek and mushrooms decreased the insulin level from 14% to 9%, but glibenclamide increased the insulin level by 29% compared to the diabetes control group (data not shown in the figure)." (PMID 39885962, 2024). "Diabetes is a complex, chronic illness due to the lack of insulin secretion (type 1 diabetes mellitus, T1DM) or a decrease in insulin sensitivity of tissues to insulin (type 2 diabetes mellitus, T2DM) with impaired carbohydrate, fat, and protein metabolism." (PMID 38765344, 2024). "As for Exubera®, it was the first of its kind, rapid-acting regular human insulin administered by oral inhalation before meals, approved in January 2006 by the FDA and European Commission (EC) as the therapy in adults with types 1 and 2 diabetes mellitus." (PMID 38255888, 2024). "In diabetes, as a consequence of the lack of insulin, GLUT4 is not translocated from the internal membrane to the plasma membrane, rendering GLUT4 ineffective." (PMID 39275349, 2024). "Type 1 diabetic patients will exhibit an absent endogenous insulin response, in combination with a glucagon response to hypoglycaemia that is lost within 5 years of the onset of diabetes." (PMID 38392992, 2024). "In an in vivo zebrafish model of diabetes, treatment with multivalent—but not monovalent—insulin nanostructures elicited a reduction in glucose levels." (PMID 37813939, 2024).